C3 (complement C3)
Diseases named in the same sentence as C3 in open-access papers (continued):
Sharing a sentence is not in itself a finding about the gene and the disease.
pulmonary oedema (3 papers, 2022 to 2024). "In the present study, the expression of C3, C3a, and C5 was increased in the lungs of rats with high-altitude pulmonary edema and a hypoxia-induced co-culture system of alveolar epithelial cells and hepatocytes." (PMID 38166725, 2024). "Pre-treatment of these mice with recombinant human soluble complement receptor-1 (rsCR1) significantly reduced the number of immune cells infiltrating the lung, minimised deposition of C3 and C5b-9 in lung vessels and decreased pulmonary oedema." (PMID 37325666, 2023).
renal cell carcinoma (3 papers, 2019 to 2023). "Eight of the top 10 genes except C3 and C4A have been reported to be implicated in renal cell carcinoma (RCC), as discussed in the next section." (PMID 31046666, 2019). "Eight of the top 10 genes in the differential gene network of KIRC except C3 and C4A have been reported to be implicated in renal cell carcinoma (RCC)." (PMID 31046666, 2019). "C1q mediated recruitment of TAM: In renal cell carcinoma, tumor cells were shown to produce high levels of C1r, C1s, C4, and C3." (PMID 34572075, 2021).
respiratory failure (3 papers, 2021 to 2022). The significant impairment of gas exchange within the lungs resulting in hypoxia, hypercarbia, or both, to the extent that organ tissue perfusion is severely compromised. "Animal studies have further demonstrated that complement C3 knockout mice are protected from lung inflammation and respiratory failure as well as inflammatory cytokines." (PMID 34276659, 2021). "When mice with complement C3 deficiency were infected with SARS-CoV, the infiltration of neutrophils and inflammatory monocytes in the lungs was strongly reduced, and the levels of cytokines and chemokines in the lungs and serum were decreased, as well as the incidence of respiratory failure." (PMID 33846344, 2021).
Respiratory tract infection (3 papers, 2020 to 2025). An infection of the upper or lower respiratory tract. "In this hypothesis-generating analysis, respiratory tract infection (OR 1.43; 95% CI 1.19–9.9; p = 0.04), proliferative lupus nephritis (OR 2.12; 95% CI 1.32–17.34; p = 0.03), and hypocomplementemia (C3 < 90 mg/dL; OR 1.72; 95% CI 1.25–10.4; p = 0.02) suggested increased odds of mortality." (PMID 41226959, 2025). "Erythrocyte sedimentation rate and C-reactive protein levels (except for the child with an on-going respiratory tract infection), differential blood cell counts, total IgA, IgE, IgM, IgG, D-dimer levels, and complement C3 and C4 levels were all unremarkable (not shown)." (PMID 37131308, 2023).
skin infection (3 papers, 2015 to 2019). An inflammatory process affecting the skin, caused by bacteria, viruses, parasites, or fungi. "Some early studies reported highly diverging results concerning total serum IgG, IgA, and IgE, and complement C3 and C4 levels in scabies patients compared to control subjects without scabies." (PMID 26492406, 2015).
synovitis (3 papers, 2008 to 2024). Inflammation of a synovial membrane. "Circulating ICs containing citrullinated fibrinogen are present in one-half of anti-CCP+ RA patients, and these ICs co-localise with C3 in the rheumatoid synovium suggesting that they contribute to synovitis in a subset of RA patients." (PMID 18710572, 2008). "Significantly higher frequency of clinical synovitis and CT-verified bone damage in C3-deficient mice strongly suggest that the absence of C3 leads to impaired bacterial clearance and a larger number of S. aureus bacteria reaching more joints." (PMID 26787717, 2016).
synucleinopathies (3 papers, 2016 to 2025). "Significant differences were also observed between the synucleinopathy patient groups (LBD and MSA) and 4RT in serum levels of C3 complement." (PMID 40029428, 2025). "At the same time, altered CSF levels of C3 and FH may not be unique to AD, as similar changes have been reported in frontotemporal degeneration and α-synucleinopathies." (PMID 26887322, 2016). "Our demonstration of targeting C3 and C5 with CP20 and RaCl is protective in our cell model against α-syn-dependent complement-mediated cytotoxicity supports complement targeting disease-modifying strategies also may hold potential in PD and other synucleinopathies." (PMID 34399786, 2021).
temporal lobe epilepsy (3 papers, 2010 to 2025). A localization-related (focal) form of epilepsy characterized by recurrent seizures that arise from foci within the temporal lobe, most commonly from its mesial aspect. "Specifically, an increase in C3 expression in the brain of patients with temporal lobe epilepsy has been shown, which is the common type in adults and is characterized by neuronal loss and gliosis in the hippocampus." (PMID 27769255, 2016).
tubulointerstitial nephritis (3 papers, 2015 to 2025). "Although hypocomplementemia is common in IgG4-related tubulointerstitial nephritis, C3 and C4 values were unavailable in our patient." (PMID 41280944, 2025). "Tubulointerstitial nephritis antigen-like precursor (TINAGL1), was linked to complement proteins, complement C3 (C3) and complement factor H (CFH) in a separate cluster." (PMID 26083627, 2015). "Drusen were also present in an individual with tubulointerstitial nephritis and C3 staining but not GN." (PMID 35497809, 2022).
tularemia (3 papers, 2017 to 2025). Tularemia is an infection caused by the bacterium Francisella tularensis. "The observation, by us and others, that WT and C3-/- mice have similar susceptibility to tularemia while C3ar1-/- mice are clearly less resistant is puzzling." (PMID 41406154, 2025). "Using a mouse model of tularemia, one study showed that C3-deficient mice had similar survival rate as WT mice after infection with LVS and that the prophylactic protection conferred by passive transfer of immune serum did not require complement." (PMID 41406154, 2025). "With the discovery of new roles for intracellular C3, a better understanding of tularemia pathogenesis is likely to emerge." (PMID 29312899, 2017). "We showed for the first time that mice deficient in C3aR1 and CR2, but not C3 or C5aR1, were more susceptible to tularemia." (PMID 41406154, 2025). "While we do not yet know all of the details of this process, C3 appears to be emerging as an important factor in the induction of macrophage death that is so commonly seen in tularemia." (PMID 29312899, 2017).
upper respiratory tract infections (3 papers, 2020 to 2024). "Treatment with “Yupingfeng San” led to increased IgG, IgM, IgA, C3, and C4 levels and decreased upper respiratory tract infections." (PMID 38050310, 2023). "We identified significant upregulation of several genes encoding components of the complement system, including C3, CFB, and C1S, uniquely within the CoV-2 dataset, in contrast to other upper respiratory tract infections (at 24 hpi)." (PMID 34786557, 2020).
urticaria (3 papers, 2020 to 2023). A vascular reaction of the skin characterized by erythema and wheal formation due to localized increase of vascular permeability. "The activation of coagulation factors and complement systems C3 and C5 have been studied on development of chronic spontaneous urticaria and it was suggested that coagulation factors and C5/C5a induce histamine release from mast cells." (PMID 37762646, 2023).
viral hepatitis (3 papers, 2016 to 2018). An acute or chronic inflammation of the liver parenchyma caused by viruses. "Viral hepatitis panel, total complement activity (CH50), C3, C4, anti-nuclear antibody (ANA), anti-neutrophil cytoplasmic antibody (ANCA), serum and urine protein electrophoresis were all unremarkable." (PMID 28975092, 2017).
vitamin D deficiency (3 papers, 2013 to 2024). A nutritional condition produced by a deficiency of VITAMIN D in the diet, insufficient production of vitamin D in the skin, inadequate absorption of vitamin D from the diet, or abnormal conversion of vitamin D to its bioactive metabolites. "Showing the impact on serum concentrations of IgG1, IgG2, IgA and complement components C4 and C3, more so in severe cases of vitamin D deficiency, but also with insufficiency of 25(OH)D, this study supports a role of vitamin D in the immune system under immunocompetent conditions." (PMID 23902738, 2013).
vitiligo (3 papers, 2015 to 2023). Generalized well circumscribed patches of leukoderma that are generally distributed over symmetric body locations and is due to autoimmune destruction of melanocytes. "Such autoantibodies, pertaining to class G immunoglobulins, have been found also in the basal layer of lesional vitiligo epidermis, in association with complement component 3 (C3) deposits." (PMID 25838868, 2015).
abscess (2 papers, 2023 to 2025). An inflammatory process characterized by the accumulation of pus within a newly formed tissue cavity which is the result of a bacterial, fungal, or parasitic infection or the presence of a foreign body. "The gingipain proteases of P. gingivalis can degrade antibody and complement opsonins, and consistent with this, we found that P. gingivalis reduced neutrophil mobilization in the mouse abscess model and decreased the level of streptococcal cell binding by C3, IgG, and IgM opsonins." (PMID 37042761, 2023).
Achalasia (2 papers, 2023 to 2024). A disorder of esophageal motility characterized by the inability of the lower esophageal sphincter to relax during swallowing and by inadequate or lacking peristalsis in the lower half of the body of the esophagus. "In the current study, complement C1q, C1s, C2, C3, C4-A, C4-B, C5, C6, and C9 were all upregulated in the achalasia group." (PMID 37324545, 2023). "Additionally, by ELISA, higher serum C3 levels in achalasia patients with respect to controls were detected." (PMID 39337632, 2024).
acquired partial lipodystrophy (2 papers, 2018 to 2025). A lipodystrophy characterized by the association of lipoatrophy of the upper part of the body and lipohypertrophy of the thighs. "In acquired partial lipodystrophy (APL), low serum complement C3, along with the presence of C3 nephritic factor and proteinuria, supports the diagnosis, while AGL may show low C4 levels." (PMID 40892266, 2025).
acute pancreatitis (2 papers, 2020 to 2021). An acute inflammatory process that leads to necrosis of the pancreatic parenchyma. "The prognostic role of complement C3 and C4 in peripheral blood in early stage of acute pancreatitis (AP) is unknown." (PMID 32187754, 2020).
ankylosing spondylitis (2 papers, 2014 to 2015). An autoimmune chronic inflammatory disorder characterized by inflammation in the vertebral joints of the spine and sacroiliac joints. "The expression levels of α-globulin, γ-globulin, immunoglobulin (Ig)G, IgA, IgM, serum complement C3, and complement C4 were found to be significantly increased in ankylosing spondylitis patients." (PMID 25452811, 2015). "The expression levels of α-globulin, γ-globulin, immunoglobulin (Ig)G, IgA, IgM, serum complement C3 and C4 were found to be significantly increased in ankylosing spondylitis patients." (PMID 25452811, 2015). "IgA and C3 accumulation were shown in kidney and skin biopsies and were considered to have a role in the pathogenesis of ankylosing spondylitis." (PMID 24653851, 2014).
Anorexia (2 papers, 2011 to 2021). Lack of desire to eat (loss of appetite). "Serum levels of C3, Factor B and D, hemolytic activity of the alternative pathway, and the inhibitors H and I were found to be low in anorexia patients and normalized with weight gain." (PMID 21542928, 2011). "Complement C3 levels did not correlate with BMI in the anorexia group alone (n = 14, Spearman correlation coefficient = 0.36, P = 0.20)." (PMID 21542928, 2011). "It is reasonable that serum C3 levels did not correlate with BMI in the anorexia group alone, reflective of the fact that a 'threshold' of severe illness from anorexia has been crossed at these profoundly low body weights, which occasioned the low C3 level." (PMID 21542928, 2011).
antibody deficiencies (2 papers, 2019 to 2021). "However, the combination of both was more strongly associated with the risk of infections than either hypogammaglobulinemia or C3 hypocomplementemia alone." (PMID 30800120, 2019). "One multivariate analysis demonstrated that hypogammaglobulinemia (IgG <6 g/L) or C3 hypocomplementemia (C3 <80 mg/dL) on Day 7 post heart transplantation were independent risk factors for infection (especially bacterial infections) and CMV disease." (PMID 30800120, 2019).
arterio(lo)sclerosis (2 papers, 2022 to 2023). "Chronic renal histology like global glomerulosclerosis, IFTA, interstitial inflammation and arterio(lo)sclerosis were significantly more prominent in patients with isolated C3 deposits." (PMID 37492933, 2023). "The top 8 variables with a higher ML score (GP) were body mass index (BMI), complement C3, serum total protein, arteriolosclerosis, urinary protein excretion during the 10-year follow-up, edema, C-reactive protein, and the Oxford E1 score." (PMID 36351996, 2022). "Herein, the ML score (GP) for MaxGD ≥ 242.3 μm identified the top 8 variables, including BMI, complement C3, serum total protein, arteriolosclerosis, urinary protein excretion (U-Prot) during the 10-year follow-up, edema, C-reactive protein, and the Oxford E1 score." (PMID 36351996, 2022).
arteritis (2 papers, 2019 to 2021). An inflammatory process affecting an artery. "Immunoglobulin G (IgG), complement component 3 (C3), and, occasionally, viral antigens are deposited in the affected glomerular capillaries, suggesting that the deposition of antigen-antibody complexes is the causal factor of arteritis." (PMID 34414315, 2021).
atrial fibrillation (2 papers, 2021). A disorder characterized by an electrocardiographic finding of a supraventricular arrhythmia characterized by the replacement of consistent P waves by rapid oscillations or fibrillatory waves that vary in size, shape and timing and are accompanied by an irregular ventricular response. "But complement factors C3 and C4 separately failed to predict risk of atrial fibrillation, whereas a combination of inflammation sensitive proteins, including C3 and C4." (PMID 33407078, 2021).
autism (2 papers, 2023 to 2024). Persistent deficits in social interaction and communication and interaction as well as a markedly restricted repertoire of activity and interest as well as repetitive patterns of behavior. "For instance, in whole-genome DNA methylation analysis, the epigenetic dysregulation of C1q, C3, and ITGB2 (C3R) was reported in autism." (PMID 37107654, 2023). "Relatedly, whole-genome DNA methylation analysis uncovered epigenetic dysregulation of several complement genes such as C1Q, C3, and ITGB2 (C3R), as well as several other inflammatory genes (e.g., TNF-α, IRF8, and SPI1) in postmortem brain samples of patients with autism." (PMID 37107654, 2023).
babesiosis (2 papers, 2014 to 2025). Babesiosis refers to a condition caused by microscopic parasites that infect the red blood cells. "Complement activation in babesiosis was confirmed by clusterin and C3 increased expression." (PMID 24885808, 2014). "Third, this case underscores the emerging recognition of complement-mediated autoimmune hemolysis in babesiosis, demonstrated by worsening hemolysis despite parasite clearance and a complement C3-positive, immunoglobulin G (IgG)-negative direct antiglobulin test." (PMID 41220440, 2025).
Behçet disease (2 papers, 2012 to 2022). "C3 and C1q serum levels have been explored as potential markers of disease activity in Takayasu arteritis, whereas data in Behçet disease are limited to in vitro observations." (PMID 35242041, 2022). "C3 and C1q serum levels have been explored in two studies as potential markers of disease activity in Takayasu arteritis, whereas data in Behçet disease are limited to in vitro observations." (PMID 35242041, 2022). "Some recently published direct immunofluorescence (DIF) studies report IgM and C3 deposits in perivascular region with or without granular C3 deposits at the dermoepidermal junction in the perilesional skin of AOU in Behçet's disease patients." (PMID 22028988, 2012).
brain hemorrhage (2 papers, 2015 to 2023).
brain inflammation (2 papers, 2012 to 2016). "When C3 was injected intracerebrally into C3 deficient mice, the extravasation of neutrophils to the lesion site was amplified, suggesting that that locally produced C3 is important in brain inflammation." (PMID 22701273, 2012).
bronchiolitis obliterans syndrome (2 papers, 2019 to 2025). A lung disorder that is mainly associated with chronic allograft dysfunction after lung transplantation and that is characterized by inflammation and fibrosis of bronchiolar walls that reduce the diameter of the bronchioles and result in progressive and irreversible airflow obstruction. "Complement activation is important in the development of acute rejection (AR) and bronchiolitis obliterans syndrome, with C3 as a key complement factor." (PMID 31616421, 2019).
Candida infection (2 papers, 2022 to 2025). "Complement deficiencies, such as C3 and C5a deficiencies, are correlated with increased susceptibility to candidiasis, underscoring the complement system’s essential role in defending against both superficial and systemic Candida infections." (PMID 40005639, 2025). "It is relevant to point out that an earlier study showed that C3 deficiency enhances susceptibility to systemic Candida infection in mice." (PMID 36211424, 2022).